SOX2 (SRY-box transcription factor 2)
Diseases named in the same sentence as SOX2 in open-access papers (continued):
Sharing a sentence is not in itself a finding about the gene and the disease.
pancreatic cancer (continued). "The extract also inhibited CD44+/CD24+/EpCAMhigh pancreatic cancer stem cell (CSC) populations, CSC-associated markers SOX2, OCT4, NANOG and CD44 in-vitro and in-vivo, and increased sensitivity to gemcitabine." (PMID 32726914, 2020). "In a study on human pancreatic tumors with ectopic SOX2 expression, deletion of SOX2 in cancer cells was shown to cause cell growth inhibition, induced by p21 and p27." (PMID 31416295, 2019). "Taken all the data together, we found that acquired gemcitabine resistant pancreatic cancer cells have elevated expression of GLI transcription factors, either GLI1 or GLI2, which is associated with elevated SOX2 expression." (PMID 30382189, 2019). "We showed that the Gli-Sox2 signaling axis is elevated in pancreatic cancer cells with acquired gemcitabine resistance." (PMID 30382189, 2019). "The relevance of SOX2 expression to human pancreatic cancer specimens was investigated using a tissue array assembled with surgically removed specimens from stage II pancreatic cancer patients enrolled in our medical center." (PMID 30382189, 2019). "Previously, we found that 6-MITC acted against tumor cell growth through mitotic arrest, the induction of apoptosis, and the inhibition of the expression of SOX2, a cancer stem cell molecule in human pancreatic cancer cells." (PMID 31771225, 2019). "Conflicting reports from SOX2 overexpression studies have also been reported for breast, prostate, and pancreatic cancers." (PMID 28388544, 2017). "We next examined the expression level changes of Bmi1, Nanog and Sox2 after gemcitabine treatment in pancreatic cancer cells with western blot analysis." (PMID 29018223, 2017). "Pancreatic cancers developed in KRAS-induced carcinomas and NUPR1-deficient mice exhibited a higher expression of stemness markers (ALDH1, SOX2, Oct-4) compared to tumors originated in NUPR1-WT mice." (PMID 29156578, 2017). "On the other hand, NFATc1 has been reported to be a transcriptional regulator of SOX2 in pancreatic cancer." (PMID 28737489, 2017). "Sox2 also has been reported to be aberrantly expressed in pancreatic cancer and contributes to cell proliferation and stemness/dedifferentiation through the regulation of a set of genes controlling G1/S transition." (PMID 26683522, 2016). "Several transcription factors, including Oct4, Nanog and Sox2, are aberrantly expressed in pancreatic cancer and contribute to pancreatic CSC-like characteristics." (PMID 25811929, 2015). "Knock-down of Snail decreased the activity of ALDH and the expressions of Sox2, Nanog, Oct4, pluripotency regulators, in pancreatic cancer cells." (PMID 26462028, 2015). "The data together suggest that the enhanced stem cell-like phenotypes of MALAT-1 on pancreatic cancer possibly through upregulating the expression of self-renewal related factors Sox2." (PMID 25811929, 2015). "Our findings are in line with previous studies, which reported that SOX2 mediated up-regulation of Slug by binding to Slug promoter in hepatocelllular carcinoma and pancreatic cancer cells." (PMID 26370982, 2015). "Specifically, the present study establishes the combination of Sox2/Oct4/c-Myc targeting as a potential anti-pancreatic cancer agent worthy of further studies in preclinical settings." (PMID 24040121, 2013). "Twist1 expression was observed in hGBMs as well as in medulloblastoma, meningioma, lung and pancreatic cancer specimens, while Sox2 expression was observed in hGBM specimens along with that of meningioma, lung and pancreatic cancers." (PMID 22184289, 2011). "In tumors, SOX2 is up-regulated in early pancreatic cancer lesions, where it is nuclear in basal cells or in the vicinity of necrotic areas and is activated in a majority of advanced tumors." (PMID 20126410, 2010).
pancreatic cancer (continued). "For example, lncRNA HOTTIP mediates HOXA9 expression to enhance Wnt/β–catenin pathway activation by binding to WDR5 in pancreatic cancer stem cells (PCSCs), leading to upregulated expression of CSC markers (CD44, CD133, and ALDH1) as well as stem-associated factors (SOX2, OCT4, LIN28, and NANOG)." (PMID 39937018, 2025). "Additionally, SOX2 is abnormally expressed in diverse types of tumours, including colorectal, gastric and pancreatic cancers." (PMID 38494478, 2024). "In conclusion, we identified the function of SOX2 in pancreatic cancer using pan-cancer analysis." (PMID 38164286, 2024). "In addition, we explored genes that are co-expressed with SOX2 in pancreatic cancer, performed Kyoto Encyclopedia of Genes and Genomes (KEGG) and Gene Ontology (GO) enrichment analysis, and verified the methylation-related indicators of SOX2." (PMID 38164286, 2024). "Furthermore, we verified the differential expression of SOX2 in pancreatic cancer cell lines by western blotting and quantitative polymerase chain reaction." (PMID 38164286, 2024). "Finally, we performed a bioinformatics study of SOX2-related immune infiltration in pancreatic cancer and showed that high SOX2 expression levels were positively correlated with Tgd, mast cell, and DC infiltration." (PMID 38164286, 2024). "Thus, we decided to analyze SOX2 using pan-cancer analysis, focusing on its significance in pancreatic cancer." (PMID 38164286, 2024). "Additionally, we compared the expression levels of SOX2 in pancreatic cancer and healthy pancreatic tissues using Wilcoxon's rank-sum test." (PMID 38164286, 2024). "MALAT1 knockdown in pancreatic cancer cells inhibited the sphere formation and the expression of self-renewal factors, including SOX2 and CD133, implying that MALAT1 may increase pancreatic CSC stemness characteristics by upregulating SOX2 expression." (PMID 39170516, 2024). "The effect of SOX2 on immune infiltration of pancreatic cancer was further revealed." (PMID 38164286, 2024). "We investigated the clinical significance of SOX2 expression in pancreatic cancer." (PMID 38164286, 2024). "Additionally, the inhibition of SOX2 expression by mir-1181 inhibits the stemness of pancreatic cancer cells." (PMID 38164286, 2024). "Studies have shown that the overexpression of OCT4, and SOX2 in pancreatic tumor organoids treated with 4 and 8 Gy of radiation can suppress the generation of reactive oxygen species (ROS), promote DNA repair in tumor cells and can lead to resistance to radiation therapy." (PMID 38429272, 2024). "SOX2 expression is undetectable in normal pancreatic acinar or ductal cells, but the ectopic expression of SOX2 has been reported for a large fraction of human pancreatic tumors and was particularly enriched in CSCs." (PMID 38012687, 2023). "Gene expression profile analysis and further experiments showed that circFARP1 conferred GEM resistance by enhancing LIF expression and secretion in CAFs, thereafter increasing the expression of ABCC2, CDA and SOX2 by activating the STAT3 signaling pathway in pancreatic cancer cells." (PMID 35045883, 2022). "Additional experiments demonstrated SOX10 and SOX2 (stem cell markers) expression in tumor organoids indicated may have some role in radiation and chemotherapy resistance in pancreatic cancer." (PMID 36713532, 2022). "Furthermore, overexpression of SOX2 correlates to gemcitabine resistance in pancreatic cancer cells, as well as higher malignancy in glioblastoma, esophageal, breast, and prostate cancers." (PMID 32457900, 2020). "Inhibition of the FGF/FGFR may provide a new approach for the treatment of SOX2-positive pancreatic cancers." (PMID 32457900, 2020). "Interestingly, increasing glucose in the culture media also showed an increase in the CD133 expression as well as expression of other cancer stem cell markers like Sox2, Oct4 and Nanog in our pancreatic cancer cell lines MIA-PaCa2 and Su86.86." (PMID 32204699, 2020).
pancreatic cancer (continued). "Finally, SOX2/Sox2 is subject to protein O-glycosylation (O-GlcNAcylation, more specifically) at residue Ser246/248 as shown in the human pancreatic cancer cell line S2VP10, as well as in murine ESCs and iPSCs." (PMID 31477842, 2020). "We tested the hypothesis that FGF/FGFR signaling influences pancreatic cancer stemness by regulating SOX2." (PMID 32457900, 2020). "Furthermore, NFATc1 levels were found to be significantly upregulated in spheroid-forming cells in pancreatic cancer, where NFATc1 promotes SOX2 transcriptionally." (PMID 33014880, 2020). "Next, we investigated how SOX2 expression was induced in the resistant pancreatic cancer cells." (PMID 30382189, 2019). "Down-regulation of GLI1, GLI2 or SOX2 sensitized pancreatic cancer cells to gemcitabine treatment." (PMID 30382189, 2019). "To determine the functional relevance of SOX2 expression with gemcitabine sensitivity in pancreatic cancer cells, we knocked down SOX2 expression by two independent shRNA constructs in the gemcitabine resistant cell lines and treated with gemcitabine afterwards." (PMID 30382189, 2019). "We have detected regulation of SOX2 by GLI transcriptional factors in pancreatic cancer cells." (PMID 30382189, 2019). "SOX2 overexpression in pancreatic cancer contributes to poor differentiation and high invasion." (PMID 31861404, 2019). "Importantly, XL184 in primary cultures of pancreatic cancer stem cells induced the inhibition of the expression of cancer stem cell markers, such as SOX2, c-met and CD133, and induced apoptosis." (PMID 29156578, 2017). "Studies have shown that OCT-4 and Nanog overexpression induced the formation of cancer stem cell-like cells through dedifferentiation and enhanced malignancy in lung adenocarcinoma, and reprogramming SOX-2 in pancreatic cancer cells also promoted the dedifferentiation process." (PMID 28179999, 2017). "To determine whether cerivastatin treatment affects invasiveness of pancreatic cancer cells, we assessed selected markers previously reported to be associated with metastatic processes in pancreatic cancer, i.e. SPP1 and SOX2." (PMID 27175805, 2016). "Similarly, SOX2 over-expression promotes self-renewal and de-differentiation of pancreatic cancer cells." (PMID 27175805, 2016). "Finally, we performed a bioinformatics study of SOX2 immune infiltration in pancreatic cancer, and the results showed that high levels of SOX2 expression were positively correlated with the infiltration of γδ T (Tgd) cells, mast cells, and dendritic cells (DCs)." (PMID 38164286, 2024). "Overexpression of circFARP1 in CAFs confers GEM resistance in pancreatic cancer cells by enhancing the expression and secretion of LIF in CAFs, thereafter activating the STAT3 signaling pathway and increasing the expression of several GEM resistance-associated factors, including ABCC2, CDA and SOX2." (PMID 35045883, 2022). "In addition, the FGFR/Akt/SOX2 signaling axis has been reported to regulate pancreatic cancer stemness properties, which means that FGFR could be a therapeutic target for aggressive cancers." (PMID 36111743, 2022). "Hence, the authors believed that the stem cell-associated genes (NANOG, POU5F1, and SOX2) may serve as promising markers and that BBR can be considered a potent anticancer agent for the treatment of pancreatic cancers." (PMID 34885950, 2021). "Besides SOX2, there are also other factors mediating cancer stemness in pancreatic cancer." (PMID 32457900, 2020). "In our experiments, SOX2-deficient pancreatic cancer cells failed to form spheres." (PMID 32457900, 2020). "Downstream targets of the Wnt/β-catenin pathway, such as SRY-box transcription factor 2 (SOX2), transcriptionally activate SP1, thereby elevating the levels of circ_0026,628 and promoting pancreatic cancer development." (PMID 40290118, 2025).
pancreatic cancer (continued). "Linc-DYNC2H1-4 acts as a ceRNA for miR-145 and facilitates the expression of its target genes, including ZEB1, a key regulator of EMT, as well as CSC markers SOX2, OCT4, NANOG, and Lin28, thereby promoting EMT and CSC activity in pancreatic cancer." (PMID 39937018, 2025). "In pancreatic cancer, NANOG forms a regulatory network with other transcription factors, such as KLF4 and SOX2, that promotes stem cell maintenance in CSCs and drives gemcitabine resistance through the upregulation of c‐Myc." (PMID 40665579, 2025). "SOX2 has been reported to contribute in tumor stemness and modulate epithelial-mesenchymal transition (EMT) in a subset of human pancreatic tumors." (PMID 38532463, 2024). "In pancreatic cancer, OGT is markedly overexpressed and catalyzes O-GlcNAcylation at the S246/248 residues of Sox2, stabilizing Sox2 in the nucleus and promoting self-renewal of tumor cells." (PMID 38473392, 2024). "In this study, we evaluated the role of pancreatic cancer stem cells (CSC) using OCT4 and SOX2, CSC markers in mouse pancreatic tumor organoids." (PMID 38429272, 2024). "Subsequently, we performed immunofluorescence analysis for the human pancreatic cancer tissues and found that the expression of IL20RB was positively correlated with the expression of NANOG and SOX2." (PMID 38098005, 2023). "The pancreatic cancer tissues of the KPNC mice exhibited enhanced expression of Ki-67, Sox-2, and other cancer stem cell biomarkers." (PMID 37714834, 2023). "CSCs obtained from primary patient-derived pancreatic cancer cells showed a positive correlation between higher telomerase activity and longer telomeres and stemness factors (NANOG, OCT3/4, SOX2, KLF4)." (PMID 37239940, 2023). "In pancreatic cancer, MBD3 regulates pancreatic cancer stem cell stemness, interacting with YAP, suppressing YAP nuclear translocation and thus suppressing both Hippo signaling and Sox2 expression." (PMID 36833308, 2023). "Part of these genes have been reported in basic studies of pancreatic cancer and are closely related to the invasion and metastasis of pancreatic cancer according to the literature, including MYC, CDH2, SNAI1, YAP1, SOX2." (PMID 35237592, 2022). "We further determined that the circFARP1/LIF axis remarkably increased the expression of GEM resistance-related genes, such as ABCC2, CDA, and SOX2, and induced GEM resistance in pancreatic cancer cells." (PMID 35045883, 2022). "We found that the co-culture of platelets and pancreatic cancer cells increased the proliferation and migration capacity of BXCP3 cells, augmented clonogenicity and induced higher levels of Nanog, Sox2 and Oct4 expression." (PMID 36232741, 2022). "The presence of SOX2 and SOX10 cancer stem cell markers in pancreatic tumor derived organoids delineates role of cancer stem cells in therapy resistance in pancreatic cancer." (PMID 36713532, 2022). "The overexpression of Sonic leads to upregulation of SOX2 and Oct4 as CSC markers in pancreatic cancer." (PMID 34769099, 2021). "An experiment has shown that BBR (15 μM) reduces expression levels of SOX2, Nanog and POU5F1 as CSC markers to impair resistance of pancreatic cancer cells to gemcitabine and suppress their progression." (PMID 34769099, 2021). "MALAT1 promotes stem cell-like phenotypes of pancreatic cancer cells via upregulating the expression of ZEB1 and self-renewal-related factor Sox2." (PMID 34660566, 2021). "The baicalein administration (0–300 μM) suppresses Sonic signaling to reduce SOX2 expression and impair CSC features in pancreatic cancer." (PMID 34769099, 2021).
pancreatic cancer (continued). "A more comprehensive regulation of stem factors in pancreatic cancer was found for linc-DYNC2H1-4, which exerted a positive effect on the regulation of ZEB1, Nanog, Sox2 and Oct by means of acting as a ceRNA of miR-145." (PMID 34203589, 2021). "Mint3 depletion decreased tumor sphere formation ability and expression of the stemness-related genes SOX2, NANOG, and LGR5 in pancreatic cancer cells." (PMID 32826949, 2020). "We previously reported that SOX2 is expressed in less than a quarter of primary PDAC tissues and only certain pancreatic cancer cell, and its expression positively correlates with sphere-forming potential." (PMID 32457900, 2020). "Our study shows that in pancreatic cancer, CD133+ cells have a high expression of GAS5, which is regulated by the self-renewal transcription factor Sox2." (PMID 31740660, 2019). "To see if in CD133+ pancreatic cancer cells Sox2 regulated GAS5 mediated growth arrest, we next silenced Sox2 (with siRNA) and studied the expression of GAS5 in CD133Hi cells." (PMID 31740660, 2019). "MALAT-1 knockdown was found to reduce levels of SOX2, suggesting regulation of SOX2 by MALAT-1 contributes to the CSC phenotype in pancreatic cancer." (PMID 28430163, 2017). "Collectively, our results demonstrate that miR-145 targets MMP3, as well as Oct4, Lin28, Nanog, Sox2 and ZEB1 which are upregulated by linc-DYNC2H1-4 in pancreatic cancer cells." (PMID 28703793, 2017). "Pancreatic cancer sphere cultured from the CFPAC-1 cells showed elevated expression of PAUF and pluripotent stemness genes (Oct4, Nanog, Stat3, and Sox2), and the mRNA of PAUF were increased in CD44+CD24+ESA+ pancreatic CSCs." (PMID 29100320, 2017). "We found that 2‐DG effectively decreased the expression of the pancreatic cancer stemness markers CD24 and CD133 and reduced the levels of pluripotency markers Nanog and Sox2 in both protein and mRNA levels." (PMID 28244691, 2017). "In the current study, Sox2, Oct-4, ABCG2, and NANOG were simultaneously upregulated in miR-629-overexpressed pancreatic cancer cells, and the expression of p21 and p27 was inversely correlated with the expression of miR-629 in pancreatic cancer cells." (PMID 29072689, 2017). "For example, in pancreatic cancer, expression of the transcription factor NFATc1 was reported to drive EMT via SOX2-dependent transcription." (PMID 28388544, 2017). "Our data strongly suggest that linc-DYNC2H1-4 acts as a sponge of miR-145 to upregulate the expression of its targets, MMP3, Oct4, Lin28, Nanog, Sox2 and ZEB1, thereby promoting EMT progression and CSC formation in pancreatic cancer cells." (PMID 28703793, 2017). "We next measured the relative mRNA levels of pluripotency marker genes of cancer stem cells, c-Met, Sox2 and Oct4, in CD133− and CD133+ pancreatic cancer cells." (PMID 26391180, 2015). "In head and neck squamous cell carcinoma (HNSCC) CSCs, autophagy promotes stemness specifically through a non-canonical FOXO3/SOX2 signaling axis, while in pancreatic cancer stem cells, it contributes predominantly to gemcitabine resistance." (PMID 40886002, 2025). "In addition, genes co-expressed with SOX2 in pancreatic cancer were explored, and KEGG and GO enrichment indicated that SOX2 was involved in multiple pathways in pancreatic cancer." (PMID 38164286, 2024). "Additionally, the co-localization of SOX2 and PSMD7 in pancreatic cancer cells was confirmed by confocal microscopy, providing further substantiation for the protein-protein interaction." (PMID 38494478, 2024). "SOX2 is a member of the SOX family and it plays an essential role in pancreatic cancer." (PMID 38164286, 2024). "SOX2, another stem cell factor, is also directly modified by OGT in pancreatic cancer cells, which protects SOX2 from degradation and increases the self-renewing capacity of pancreatic cancer cells." (PMID 37838167, 2023).